TNFRSF21 (TNF receptor superfamily member 21)
Diseases named in the same sentence as TNFRSF21 in open-access papers (continued):
Sharing a sentence is not in itself a finding about the gene and the disease.
esophageal squamous cell carcinoma (1 paper, 2022). Esophageal squamous cell carcinoma (ESCC) is a type of esophageal carcinoma (EC) that can affect any part of the esophagus, but is usually located in the upper or middle third. "Studies suggested that TNFRSF21 might serve as a prognostic marker for esophageal squamous cell carcinoma and esophagus adenocarcinoma." (PMID 35957699, 2022).
Hyperglycemia (1 paper, 2022). An increased concentration of glucose in the blood. "Further experiments confirmed that advanced glycation end products (AGEs), the metabolite derived by hyperglycemia, increased the expression of TNFRSF21 in CAECs." (PMID 35740304, 2022).
influenza (1 paper, 2016). An acute viral infection of the respiratory tract, occurring in isolated cases, in epidemics, or in pandemics; it is caused by serologically different strains of viruses (influenzaviruses) designated A, B, and C, has a 3-day incubation period, and usually lasts for 3 to 10 days. "Notable among immune-related positional candidates are Tnfrsf21, and Pla2g7 implicated in influenza control, though its effect was limited to male mice." (PMID 26845690, 2016).
left ventricular hypertrophy (1 paper, 2022). Enlargement of the LEFT VENTRICLE of the heart. "In addition, levels of serum TNFRSF21 were higher in type 2 DM patients with left ventricular hypertrophy (LVH) than those without LVH." (PMID 35740304, 2022).
lymph node metastasis (1 paper, 2025). "A subsequent investigation of associations demonstrated that UGCG and TNFRSF21 expression levels showed a positive relationship with NAC, whereas the expression of BTG2 and MYB, as well as the lymph node metastasis, were negatively correlated with the efficacy of NAC." (PMID 40332226, 2025). "The chi-square test and Fisher’s exact test indicated that postoperative RCB classification demonstrated a statistically significant correlation with the expression levels of UGCG, BTG2, TNFRSF21, and MYB, as well as lymph node metastasis in BRCA patients prior to NAC." (PMID 40332226, 2025). "Specifically, patients were more likely to achieve a higher RCB classification when they were negative for UGCG and TNFRSF21, but positive for BTG2 and MYB, with no lymph node metastasis." (PMID 40332226, 2025).
Nephroblastoma (1 paper, 2023). An embryonal neoplasm characterized by the presence of epithelial, mesenchymal, and blastema components. "At the same time, we observed downregulation of some pro-inflammatory factors: TNFRSF21, apolipoprotein E (APOE), nephroblastoma-overexpressed protein (NOV), and PDZ-binding protein (PBK)." (PMID 36829800, 2023).
primary immunodeficiency (1 paper, 2022). "KEGG results indicated that spliceosome and steroid hormone biosynthesis were positively correlated with TNFRSF21, whereas neuroactive ligand receptor interaction and primary immunodeficiency were negatively associated with TNFRSF21." (PMID 35606813, 2022).
Sepsis (1 paper, 2024). Sepsis is defined as life-threatening organ dysfunction caused by a dysregulated host response to infection. "Low expression of ARHGEF10L in CD14 + monocytes is associated with increased death from sepsis, and the list included genes related to anti-bacterial activity (LCN2), regulation of TLR4 responses (SLC15A3), LPS sensitivity and autophagy (RUBCNL and SLC8A1) and apoptosis (FAS, TNFRSF21, TNFRSF8)." (PMID 39730996, 2024).
skin cutaneous melanoma (1 paper, 2025). "TNFRSF21, linked to necroptosis, has been associated with skin cutaneous melanoma prognosis." (PMID 40109864, 2025).
squamous cell carcinoma of (1 paper, 2022). "Besides, a study demonstrated that the TNFRSF21 expression was strongly negatively linked to the miR-20a-5p expression, and the downregulation of TNFRSF21 functioned as an oncogene in squamous cell carcinoma of the head and neck." (PMID 36437961, 2022).
type 2 diabetes (1 paper, 2023). "TNFRSF21 has recently been shown to play a pathogenic role in heart disease in patients with type 2 diabetes." (PMID 37569434, 2023).
uveitis (1 paper, 2025). An inflammatory process affecting a part of or the entire uvea. "For instance, in the uveitis only group, the genes KLHL21, MYLIP, ZNFX1, PDE4A, TNFRSF21, and N4BP2L2 were downregulated, while METTL72, GAPT, CD180, CCR2, and TLR7 were upregulated when comparing uveitis patients with healthy controls." (PMID 40270958, 2025).
tumor (75 papers, 2010 to 2025). "Oppositely, upregulation of CARD6 and TNFRSF21 in tumor samples was associated with lower risk of early local recurrence after dCRT." (PMID 34488754, 2021). "It was observed that forced expression of TNFRSF21 contributed to tumor cell proliferation and DDP resistance." (PMID 40109864, 2025). "The differential mRNA expression analysis of genes included in the AVENIO surveillance panel demonstrated that MET, EGFR, SLPI, and TNFRSF21 had the highest difference in log2(TPM + 1) between NSCLC tumours and PBMCs." (PMID 36825535, 2023). "Using TCGA database, the expression level of TNFRSF21 in PAAD tumor tissues and normal pancreatic samples was analyzed." (PMID 35606813, 2022). "Firstly, we noticed that TNFRSF21 was clearly upregulated in both LUAD tumor tissues and NCI-H2009 and A549 cells compared with normal groups, respectively." (PMID 35936736, 2022). "In our results, we found that APP and its binding partner TNFRSF21 were also highly expressed in tumor-related B-cells." (PMID 33777800, 2021). "In the solid compared to the non-solid, TNF expressed in multiple immune cells (Treg, B, DC, CD8 T, CD4 T and macrophages) interacted with TNFRSF21 in epithelial cells which may enhance tumor cell survival and immune evasion 106,107." (PMID 39803458, 2025). "This correlation suggests that in the Basal subtype, LINC02188 may enhance the release of tumor angiogenesis factors (TNFRSF21, PRG2) by augmenting RNA methylation, consequently promoting angiogenesis." (PMID 38408075, 2024). "The compound of APP and death receptor 6 (DR6/TNFRSF21) inhibited the activation of necroptosis of vascular endothelial cells, resulting in significant reduction in transdermal migration of tumor cells, thus controlling tumor metastasis." (PMID 35237304, 2022). "Death receptor 6 (TNFRSF21) has been reported to have inhibitory effects on monocyte differentiation when cleaved from the surface of tumor cells by matrix metalloproteinase 14 (MMP14), the latter being expressed about 10-fold higher in ncM and intM (data not shown)." (PMID 35967310, 2022). "For example, TNFRSF21 (DR6, death receptor 6), showing increased expression in CR samples, is considered a marker of tumor-associated vascular endothelium and a mediator of tumor cell migration." (PMID 32899940, 2020). "Moreover, TNFRSF21 was significantly upregulated in PAAD tumor tissues and cell lines." (PMID 35606813, 2022). "TNFRSF21, also known as death receptor 6 (DR6), is a cell surface receptor of the tumor necrosis factor receptor superfamily, and has been involved in various cellular events, including apoptosis and tumor growth, although its role in endothelial cell injury of CVD in DM has not been explored." (PMID 35740304, 2022). "Among that, the protein expression of TNFRSF21, JAG1, and SPP1 were evidently up-regulated in tumor than normal tissues." (PMID 36274838, 2022). "FASLG, TNFRSF1B, GATA3, TARDBP, ZBP1, TNFRSF21, and TLR3 are mainly expressed in multiple immune cell types, and immune cells have a role in TME to inhibit tumor progression." (PMID 35899194, 2022). "In this work, we illustrated that lncRNA MIR31HG and TNFRSF21 were over-expressed, while miR-193a-3p was downregulated in human LUAD tumor tissues and cells." (PMID 35936736, 2022). "The TNFRSF21 is a member of the TNF/TNFR family and plays a critical role in pathogen recognition, immune response, inflammation, and tumor progression." (PMID 34449805, 2021). "The profiling data showed that 7 apoptosis-related genes were concordantly > twofold downregulated in recurrent tumor samples compared with the expression in paired primary tumor samples, including AKT1, BAG4, BCL2A1, BFAR, CARD6, CASP8 and TNFRSF21." (PMID 34488754, 2021). "Based on the intersection of TNF receptor superfamily signature between human BC tissues and cell lines to exclude the tumor heterogeneity, both TNBC tissues and cell lines dominantly expressed TNFRSF21." (PMID 30728901, 2019).
tumor (continued). "In this sense, we evaluated the prognostic value of the ZNF611, ZNF304, RIPK1, TNFRSF21, DUSP8 and HRAS genes according to tumor subtypes." (PMID 30938061, 2019). "Given that the APP‒TNFRSF21 axis mediates tumor cell-induced endothelial necroptosis, we inferred that APP+ epithelial cells might induce necroptosis of FOLR2+ macrophages via the APP‒TNFRSF21 axis." (PMID 39702278, 2024). "Tumor samples from high-risk group A showed a higher mean overall IHC score for Anti-MSX1, Anti-CD271, Anti-ERRFI1, Anti-PTPRF, Anti-TNFRSF21, Anti-TNFRSF12a, and Anti-IGFBP2, but without significance." (PMID 30641895, 2019). "The secreted proteins CCL2, TNFRSF21, PLC, COL1A1, PlGF, PAI and IL-6 are all known to be involved in cancer progression and have pro-tumorigenic properties, suggesting that cancer cells can be shifted towards a more aggressive state by tumor microenvironmentally induced secretion." (PMID 34090457, 2021). "TNFRSF21 (tumor-necrosis factor receptor superfamily 21, as known as death receptor 6, DR6) in a lacking animal model showed reduced tumor metastasis capability." (PMID 36836481, 2023).
cancer (31 papers, 2012 to 2025). A tumor composed of atypical neoplastic, often pleomorphic cells that invade other tissues. "Numerous research studies have documented the possible involvement of TNFRSF21 in various cancers." (PMID 40109864, 2025). "Ectopic TNFRSF21 expression modulated cancer stem cell properties and sensitivity to DDP." (PMID 40109864, 2025). "Additionally, the average expression of TNF-related genes, including TNFRSF1A, TNFRSF1B, TNFSF10, and TNFRSF21, was higher than that of most other necroptosis genes in pan-cancer." (PMID 37000317, 2023). "As per the QPCR array data, Rapamycin is believed to induce apoptosis in cancer cells by altering the components of the extrinsic (CD40LG, DAPK1, LTA, TNFRSF21) and intrinsic (BIRC5, BNIP3) apoptotic pathways as well as the TP73 upstream modulator." (PMID 38276004, 2024). "Of these DEGs, 6 (EGFR, GATA3, DIABLO, CFLAR, RIPK3, and MAPK8) were repressed, while (ZBP1, PLK1, SPATA2, BCL2, ALK, FASLG, TNFRSF21, and LEF1) were upregulated in cancer cases." (PMID 35610275, 2022).
heart disease (2 papers, 2022 to 2023). "In conclusion, TNFRSF21 plays a pathogenic role in heart disease of type 2 DM, and can be used as a biomarker of the impairment of cardiac structure and function in type 2 DM patients." (PMID 35740304, 2022).
TNFRSF21 also shares sentences with these, for which no sentence is quoted: autoimmune disease (5 papers); amyotrophic lateral sclerosis (3); infection (3); Autoimmunity (2); bladder cancer (2); cervical tumor (2); colorectal cancer (2); gastric cancer (2); leukaemia (2); osteoarthritis (2); ovarian tumors (2); pemphigus vulgaris (2); prion disease (2); sarcoma (2); acute kidney injury (1); alcoholic hepatitis (1); amyloid (1); angiosarcoma (1); Arthritis (1); asthma (1); bone sarcoma (1); Bovine mastitis (1); carcinosarcoma (1); chondrosarcoma (1); chronic lymphocytic leukemia (1); colitis (1); COVID-19 (1); dementia (1); depression (1); diabetes (1).
A further 38 diseases each share a sentence with TNFRSF21 in 1 paper.